VRK1 (VRK serine/threonine kinase 1)
Diseases named in the same sentence as VRK1 in open-access papers (continued):
Sharing a sentence is not in itself a finding about the gene and the disease.
Cerebral ischemia (1 paper, 2023). Restriction of arterial blood supply to the brain associated with insufficient oxygenation to support the metabolic requirements of the tissue. "In the current study, we examined the role of Circ VRK1 in cerebral ischemia-reperfusion injury." (PMID 36707796, 2023). "Therefore, in this study, we hypothesized that Circ VRK1 targets miR-17 to modulate PTEN-mediated PI3K/AKT signaling, thus involving in the development of cerebral ischemia-reperfusion injury." (PMID 36707796, 2023).
Cognitive impairment (1 paper, 2018). Abnormal cognition is characterized by deficits in thinking, reasoning, or remembering. "In order to examine if reduced Vrk1 expression causes motor or cognitive impairment, we performed a set of behavioral experiments in Vrk1GT3/GT3 vs. Vrk1+/+ mice." (PMID 30050127, 2018).
distal motor neuropathies (1 paper, 2020). "Functionally, this impaired VRK1 kinase activity implicates a loss of functions, which have to be linked to distal motor neuropathies and SMA phenotype." (PMID 32365420, 2020). "Among the distal motor neuropathy phenotypes associated with human VRK1 mutations are SMA,17, 20, 23, 24, 25 ALS,19, 20 and pontocerebellar hypoplasia." (PMID 32365420, 2020).
female sterility (1 paper, 2024). "In a murine gene-trap model of VRK1, deficiency in levels of VRK1 causes male sterility by impairing the formation of spermatogonia, and female sterility by causing defective folliculogenesis and interfering with the progression of oogenesis." (PMID 38753965, 2024). "In mice, deficiency of VRK1 causes male and female infertility due to a progressive loss of spermatogonia and impaired oogenesis by defects in folliculogenesis and meiotic recombination." (PMID 38753965, 2024).
gastric cancer (1 paper, 2023). A primary or metastatic malignant neoplasm involving the stomach. "Among them, the therapeutic effect of gene immunization on LUSC has gradually become a hot topic of research, although the effect of VRK1 on the migration and invasion of gastric cancer cells has been demonstrated." (PMID 37547297, 2023).
invasive breast carcinoma (1 paper, 2018). A carcinoma that infiltrates the breast parenchyma. "Using public databases, we determined that VRK1 is among the top 10% of overexpressed transcripts in multiple subtypes of invasive breast cancer, and that high levels of VRK1 expression are correlated with decreased relapse-free survival." (PMID 30180179, 2018). "Comparing normal breast tissue to tumors of all sub-types within this dataset, we determined that VRK1 ranked within the top 5% or 10% of overexpressed genes in the majority of invasive breast cancer subtypes." (PMID 30180179, 2018). "Upon analyzing the Curtis Breast database, which profiles the expression of >19,273 genes in >2,000 cases, VRK1 was in the top 5% or 10% of genes that were upregulated in multiple sub-types of invasive breast carcinoma relative to normal breast tissue." (PMID 30180179, 2018).
laryngeal carcinoma (1 paper, 2022). Carcinoma that arises from the laryngeal epithelium. "The mutual influence of VRK1 and NOTCH pathways is related to the prognosis of laryngeal cancer." (PMID 35559251, 2022).
male infertility (1 paper, 2022). The inability of the male to effect fertilization of an ovum after a specified period of unprotected intercourse. "Partial KO of Vrk1 by gene trapping resulted in a slight reduction in brain size, mild motor dysfunction, and male infertility in mice." (PMID 36040810, 2022).
microcephaly-complex motor and sensory axonal neuropathy syndrome (1 paper, 2023). Microcephaly-complex motor and sensory axonal neuropathy syndrome is an extremely rare subtype of hereditary motor and sensory neuropathy characterized by severe, rapidly-progressing, distal, symmetric polyneuropathy and microcephaly (which can be evident in utero) with intact cognition. "VRK1 encodes a Serine/Threonine Kinase and is associated with pontocerebellar hypoplasia, Type 1A and Microcephaly-Complex Motor and Sensory Axonal Neuropathy Syndromes." (PMID 36869353, 2023).
non-small cell lung carcinoma (1 paper, 2021). A group of at least three distinct histological types of lung cancer, including non-small cell squamous cell carcinoma, adenocarcinoma, and large cell carcinoma. "VRK1 is overexpressed in several types of cancers, including non-small cell lung cancer; however, there is a lack of data on the control of VRK1 gene expression, primarily regarding the mechanism of post-transcriptional control of VRK1 expression." (PMID 34071140, 2021).
Pontocerebellar atrophy (1 paper, 2021). Atrophy affecting the pons and the cerebellum. "VRK1 mutations have also been associated with an atypical form of infantile spinal muscular dystrophy with only lower motor neuron findings and pontocerebellar atrophy." (PMID 34946884, 2021).
rectal cancer (1 paper, 2016). A primary or metastatic malignant neoplasm that affects the rectum. "This study provides novel data on the role of VRK1 and VRK2 in predicting tumor response to NACRT, and we propose a model with high predictive ability which could have a substantial impact on clinical management of locally advanced rectal cancer." (PMID 27456229, 2016). "The impact of the VRK1 and VRK2 kinases in rectal cancer is a novel contribution, providing further insight on the potential role for these kinases in cancer and also representing a new tool for the prediction of response to neoadjuvant treatment in patients with locally advanced rectal cancer." (PMID 27456229, 2016).
retinoblastoma (1 paper, 2008). A malignant tumor that originates in the nuclear layer of the retina. "In cells without retinoblastoma, that functionally mimic its phosphorylation, there is an overexpression of VRK1, consistent with the permanence of these cells in a cycling state." (PMID 18286197, 2008).
sensorimotor neuropathies (1 paper, 2025). "Variants of VRK1 may cause sensorimotor neuropathy without neurodevelopmental abnormalities with an onset after the age of 40 with a slow gradual progression." (PMID 40428407, 2025).
Sensory neuropathy (1 paper, 2021). Peripheral neuropathy affecting the sensory nerves. "Several gene mutations had additional clinical features: FUS with myoclonic jerks and tremor; SETX with some cerebellar features; ALS2 with early anarthria and pseudobulbar affect; and VRK1 with sensory neuropathy." (PMID 34946884, 2021).
silicosis (1 paper, 2020). Silicosis is a respiratory disease caused by breathing in (inhaling) silica dust. "We next found that the PTPN2, Factor B, and VRK1 concentrations in silicotic rats silicosis and SiO2-stimulated MLE-12 cells were significantly higher than control groups." (PMID 32054021, 2020). "In conclusion, we found three proteins, PTPN2, factor B, and VRK1, to be significantly upregulated in silicosis." (PMID 32054021, 2020). "This study verified that Protein PTPN2, factor B, and vaccinia-related kinase 1 (VRK1) were significantly upregulated in rat silicosis and SiO2-stimulated MLE-12." (PMID 32054021, 2020).
sterility (1 paper, 2010). "VRK1 is known to play a role in germ cell development, and its deficiency results in sterility." (PMID 21179456, 2010).
Stillbirth (1 paper, 2018). Death of the fetus in utero after at least 22 weeks of gestation. "Fourteen SNPs between the PAPOLA (poly(A) polymerase alpha) and the VRK1 (vaccinia related kinase 1) genes were associated with the number of stillbirths in the continuously married subset (p ≥ 8.38×10−9)." (PMID 30188897, 2018).
vascular tumor (1 paper, 2022). "Univariate analysis showed that the maximum pathological diameter of the tumor, whether adjuvant chemotherapy, the presence or absence of vascular tumor thrombus, T stage, and VRK1 expression are factors that affect the patient’s OS (p < 0.05)." (PMID 35559251, 2022).
Wilms tumor (1 paper, 2022). An embryonal neoplasm characterized by the presence of epithelial, mesenchymal, and blastema components. "VRK1 may provide new potential biomarkers for improving the prognosis and treatment of Wilms tumor (WT) patients by showing the WNT signaling pathway." (PMID 35559251, 2022).
tumor (43 papers, 2008 to 2025). "Here, we demonstrated that VRK1 expression is elevated in HCC tumor tissues, which is associated with high tumor stage and poor prognosis in HCC patients." (PMID 40234378, 2025). "In HCC, VRK1 modulates G1/S cell cycle transition, cell proliferation and is associated with tumor immune infiltration anti-PD-L1 immunotherapy response." (PMID 40234378, 2025). "Circ-VRK1 expression was associated with smaller tumor size, reduced T stage, and lower Tumor, Node, Metastasis (TNM) stage." (PMID 39684767, 2024). "VRK1 has been associated with the control of cell proliferation and mitosis, and is expressed at high levels in proliferating and tumor cells, which is an indicator of a poorer prognosis in many tumor types." (PMID 37179361, 2023). "The functionality of VRK1 is dual, as it can act as either an oncogenic driver, a tumor suppressor, or a gene predisposing to cancer." (PMID 38157278, 2023). "We observed that VRK1 expression was increased in most cancer types and that high levels of VRK1 were associated with poor survival outcomes and tumor progression in some cancers." (PMID 38157278, 2023). "Further COX regression analysis indicated that the expression of VRK1 is an independent risk factor affecting tumor progression." (PMID 35559251, 2022). "The results of Cox multivariate analysis showed that the expression of VRK1 is an independent risk factor affecting tumor progression." (PMID 35559251, 2022). "In conclusion, we finally identified five genes most associated with tumor progression and prognosis: VRK1, NUP37, HMMR, SPC25, and RUVBL1." (PMID 36052378, 2022). "Cox multi-factor analysis results show that VRK1 expression is an independent risk factor affecting tumor progress." (PMID 35559251, 2022). "We have identified that VRK1 is associated with cell proliferation in NB tumor cells and that it is an essential gene controlling cell division in these tumors." (PMID 33233777, 2020). "In this study we have identified that the human protein kinase VRK1 is associated with tumor aggressiveness and patient survival in NB." (PMID 33233777, 2020). "In the context of tumor growth, the human VRK1 protein has been implicated in the regulation of proliferation and cell cycle progression, where it plays several roles." (PMID 29679095, 2018). "In this latter context, the role of VRK1 is similar to that of other tumor suppressor genes or tumor predisposition genes." (PMID 27334688, 2016). "A high VRK1 level was found to be a significant risk factor for recurrence, as were other common prognostic factors, including Edmonson grade, tumor size and tumor stage." (PMID 26375549, 2015). "The accumulation of VRK1 is likely to drive to progression of cell division and thus expand a cell population that is mutated and implicated in tumor development." (PMID 21386980, 2011). "Moreover, VRK1 functional downregulation by mutation or inhibition sensitizes tumor cells to genotoxic treatments." (PMID 38753965, 2024). "Additionally, Spearman's correlation analysis was employed to explore the potential associations between VRK1 expression and various factors, including tumor microenvironment scores, immune cell infiltration, and immune-related genes." (PMID 38157278, 2023). "Furthermore, we discovered that VRK1 was closely linked to TME, tumor infiltration immune cells, immune subtypes, and biomarkers of ICIs, providing new insights into the role of VRK1 in tumor immunity." (PMID 38157278, 2023). "Furthermore, the promoter methylation status of VRK1 varied across different tumor types, and this variation was associated with patient prognosis in certain cancers." (PMID 38157278, 2023). "Moreover, we identified a close association between VRK1 expression and the tumor microenvironment (TME), tumor-infiltrating immune cells, immune subtypes, and immune checkpoint inhibitors (ICIs) biomarkers." (PMID 38157278, 2023).
tumor (continued). "Moreover, when VRK1 is downregulated, it causes G1 cell cycle arrest and reduced proliferation of tumor cells." (PMID 25310002, 2014). "Moreover, VRK1 overexpression is associated with a poor prognosis in several tumor types." (PMID 38732093, 2024). "In this work, we have studied the implications of VRK1 on the cellular sensitivity to oxidative stress and its role in the modification of histone post-translational modifications and the nuclear phosphoproteome, which underly the sensitization of tumor cells to treatments based on DNA damage." (PMID 38732093, 2024). "Furthermore, VRK1 is associated to tumor cell proliferation, including neuroblastoma cells." (PMID 34195200, 2021). "However, based on the biological actions of VRK1, either in cell proliferation or DNA damage responses indicates that depending on the cellular context, VRK1 might function as an oncogene or a tumor suppressor or predisposition gene." (PMID 29679095, 2018). "In addition, suppressing VRK1-mediated BAF phosphorylation by the small-molecule inhibitor obtusilactone B induces abnormal nuclear envelope dynamics and tumor cell death, consistent with our finding that luteolin-mediated VRK1 inhibition causes similar phenomena." (PMID 25310002, 2014). "IHC results further showed that CRC tumor tissues exhibited higher levels of VRK1 protein expression than adjacent normal tissues." (PMID 40384864, 2025). "The results showed that VRK1 was significantly overexpressed in HCC tissues compared with the non-tumor liver tissues." (PMID 40234378, 2025). "VRK1 exhibits elevated expression levels in tumor cells and normal cells and in tissues with high proliferation rates." (PMID 39940790, 2025). "To further investigate the effects of VRK1 on tumor formation and growth in vivo, we constructed a xenograft tumor model in BALB/c nude mice." (PMID 40234378, 2025). "The study demonstrated elevated mRNA and protein expression levels of BANF1 and VRK1 in tumor tissues relative to adjacent normal tissues." (PMID 40384864, 2025). "In vitro and in vivo experiments manifested that VRK1 overexpression significantly promotes cell proliferation, colony formation, migration and tumor growth of HCC by inducing epithelial-mesenchymal transition (EMT) program." (PMID 40234378, 2025). "The tumor growth rate of mice in the VRK1 knockdown group was noticeably slower than that of the control group." (PMID 40234378, 2025). "Remarkably, the protein expression of VRK1 also exhibited a positive correlation with SNAI1 expression in mice tumor tissues." (PMID 40234378, 2025). "In the context of cancer, the inhibition of VRK1 activity has the potential to be a vulnerability in tumor cells and thus become a target for use in novel synthetic lethality strategies in cancer treatment." (PMID 38753965, 2024). "VRK1 is overexpressed in tumors, facilitating tumor progression and resistance to genotoxic treatments." (PMID 38753965, 2024). "High levels of VRK1 facilitate tumor cell proliferation, resistance to treatments based on DNA damage, and epithelial-mesenchymal transition in breast cancer cells." (PMID 38753965, 2024). "High levels of VRK1 promote tumor cell expansion by enhancing cell proliferation and resistance to treatment." (PMID 38753965, 2024). "The VRK1 roles vary depending on the phase of the cell cycle; in some contexts, it promotes tumor growth and in others tumor prevention." (PMID 38732093, 2024). "And in vivo experiments showed that downregulation of VRK1 inhibited tumor growth and promoted tumor cell apoptosis, and the effect was enhanced after combining with DOX, which showed a strong antitumor effect with certain clinical significance." (PMID 37547297, 2023).
tumor (continued). "In the present study, we found that both VRK1 downregulation and DOX administration inhibited tumor growth, and the combined effect of VRK1 downregulation and DOX on promoting LUSC apoptosis was greater than that of DOX alone." (PMID 37547297, 2023). "The comprehensive expression profiles of VRK1 across primary tumors, pathological stages, and metastatic conditions further suggest its involvement at various stages of tumor progression." (PMID 38157278, 2023). "VRK1 is highly expressed in a variety of tumor cells and is positively correlated with tumor cell proliferation, tumor progression, and poor prognosis." (PMID 36770809, 2023). "In most tumors, VRK1 was positively associated with the infiltration of progenitors of lymphoid, and MDSC, suggesting that VRK1 was likely to affect tumor development and prognosis by impacting the tumor microenvironment." (PMID 38157278, 2023). "Numerous studies have demonstrated that VRK1 is differentially expressed in different tumors and has a regulatory role in tumor development." (PMID 37547297, 2023). "This VRK1 inhibitor can be of use for designing novel synthetic lethality strategies to promote tumor cell death." (PMID 36902348, 2023). "The results showed that VRK1 was heterogeneous and expressed at different levels in tissues and tumor cells." (PMID 38157278, 2023). "This comprehensive analysis provides valuable insights into the potential interplay between VRK1 and immune-related genes, shedding light on its role in modulating the tumor immune microenvironment." (PMID 38157278, 2023). "The model successfully included 4 independent prognostic factors, including tumor diameter, adjuvant chemotherapy, T stage, and VRK1 expression." (PMID 35559251, 2022). "Meanwhile, we found that compared with the paracancerous tissues in the TCGA database, the mRNA expression of VRK1 in tumor tissues is upregulated." (PMID 35559251, 2022). "The results suggest, compared with the blank control group (shVRK1-NC) tumor-bearing tissue, the expression of VRK1 in the tumor-bearing tissue of the knockdown group (shVRK1-2) was significantly reduced." (PMID 35559251, 2022). "Further immunohistochemistry results of tumor-bearing tissues suggested that the expression of VRK1 in tumor-bearing tissues of the knockdown group (shVRK1-2) was significantly lower than that of the blank control group (shVRK1-NC)." (PMID 35559251, 2022). "The tumor tissues and paracancerous tissues of the patients included in the study were taken to compare the VRK1 expression." (PMID 35559251, 2022). "Once the xenografts reached approximately 200 mm3, VRK1 KO in tumor cells was induced by intraperitoneal administration of tamoxifen." (PMID 36040810, 2022). "We found that CNS and PNS tumors exhibited the lowest expression of VRK2 across all tumor lineages, while VRK1 expression was slightly reduced in CNS/PNS tumors as compared with all other tumor lineages." (PMID 36040810, 2022). "Decreased tumor growth corresponded to increased survival of mice with VRK1-KO neurospheres (P = 0.1)." (PMID 36040810, 2022). "Knockdown screenings have identified VRK1 as a druggable kinase that will interfere with tumor cell viability and sensitizes cells to genotoxic drugs and radiation." (PMID 36011043, 2022). "VRK1 KO resulted in virtually complete and durable tumor remission in all mice (n = 10 tumors) 10–20 days following tamoxifen treatment, whereas tumors in vehicle-treated controls continued exponential growth." (PMID 36040810, 2022). "VRK1 is highly expressed in many tumor types and confers resistance to genotoxic treatments in different tumors." (PMID 34195200, 2021). "Depletion of the chromatin kinase VRK1 promotes tumor cell death at lower doses of a combination of temozolomide and olaparib treatments, and can be a novel alternative target for therapies based on synthetic lethality." (PMID 34195200, 2021).